MDH1 (malate dehydrogenase 1)
Description:
Catalyzes the reduction of aromatic alpha-keto acids in the presence of NADH. Plays essential roles in the malate-aspartate shuttle and the tricarboxylic acid cycle, important in mitochondrial NADH supply for oxidative phosphorylation. Catalyzes the reduction of 2-oxoglutarate to 2-hydroxyglutarate, leading to elevated reactive oxygen species (ROS).
Synonyms: KAR; MDHA; DEE88; EIEE88; HEL-S-32; MDH-s; MGC:1375; MOR2
Tractability: PROTAC: UniProt records ubiquitination sites on it; ubiquitination databases record sites on it; its protein half-life has been measured; a small molecule that binds it is known.
Target class: Enzyme; Oxidoreductase
Gene: Protein-coding gene on chromosome 2 (63,588,557 to 63,607,273, forward strand). Ensembl gene ENSG00000014641.
Subcellular location: Cytoplasm, cytosol
Subcellular location (Human Protein Atlas): Centrosome; Cytosol
Pathways (Reactome):
Metabolism: Malate-aspartate shuttle
Gene Ontology:
Molecular function: (2R)-hydroxyphenylpyruvate reductase [NAD(P)H] activity; L-malate dehydrogenase (NAD+) activity; protein binding; malic enzyme activity; (S)-2-hydroxyglutarate dehydrogenase activity; catalytic activity; malate dehydrogenase activity; oxidoreductase activity; oxidoreductase activity, acting on the CH-OH group of donors, NAD or NADP as acceptor
Biological process: malate-aspartate shuttle; NAD+ metabolic process; NADP+ metabolic process; malate metabolic process; oxaloacetate metabolic process; tricarboxylic acid cycle
Cellular component: cytoplasm; cytosol; extracellular exosome; extracellular region
Genetic constraint (gnomAD): Loss-of-function variants: 9 observed, 23.31 expected, observed/expected ratio (o/e) 0.39, 90% interval 0.23 to 0.67. The upper end of that interval is the gene's LOEUF score, 0.67, which puts it in group 2 of 6, group 1 being the genes least tolerant of losing a copy. Missense variants: 277 observed, 299.82 expected, observed/expected ratio (o/e) 0.92, 90% interval 0.84 to 1.02. Synonymous variants: 115 observed, 106.13 expected, observed/expected ratio (o/e) 1.08, 90% interval 0.93 to 1.26.
Homologues: Orthologues: chimpanzee MDH1 (99% identical), macaque MDH1 (99% identical), rat Mdh1 (97% identical), rabbit MDH1 (97% identical), mouse Mdh1 (96% identical), guinea pig MDH1 (96% identical), pig MDH1 (96% identical), dog MDH1 (95% identical), tropical clawed frog mdh1 (87% identical), zebrafish mdh1aa (78% identical), zebrafish mdh1ab (78% identical), Drosophila melanogaster Mdh1 (66% identical), and 1 more. Paralogues in human: MDH1B (28% identical).
Diseases named in the same sentence as MDH1 in open-access papers:
MDH1 is named in the same sentence as 64 diseases in open-access papers, as found by Europe PMC text mining. Sharing a sentence is not in itself a finding about the gene and the disease. The quoted sentences say what the papers report.
pancreatic ductal adenocarcinoma (12 papers, 2020 to 2025). An infiltrating adenocarcinoma that arises from the epithelial cells of the pancreas. "The gene MDH1 regulates autophagy in pancreatic ductal adenocarcinoma (PDAC) associated with PDAC cell survival." (PMID 37151882, 2023). "For example, oxidative stress contributes to pancreatic ductal adenocarcinoma via inhibiting the arginine methylation of malate dehydrogenase 1 (MDH1)." (PMID 38474405, 2024). "O-GlcNAcylation enhances MDH1 activity to promote proliferation of pancreatic ductal adenocarcinoma cells." (PMID 37151882, 2023). "For example, MDH1 promoted pancreatic ductal adenocarcinoma cell proliferation and metabolism through NAD production to support glycolysis." (PMID 34044809, 2021). "Additionally, MDH1 enhances pancreatic ductal adenocarcinoma's resistance to oxidative stress and supports cell proliferation and tumor growth." (PMID 40963902, 2025). "Additionally, pancreatic ductal adenocarcinoma (PDAC) cells exhibit increased glycosylation of malate dehydrogenase 1 (MDH1), facilitating glutamine metabolism and promoting tumor survival under metabolic stress conditions." (PMID 40868286, 2025). "PRMT4 has also been shown to suppress glutamine metabolism in pancreatic ductal adenocarcinoma by methylating malate dehydrogenase 1 (MDH1), or inhibits HCC glycolysis by methylating glyceraldehyde-3-phosphate dehydrogenase, both leading to reduced growth and proliferation of cancer cells." (PMID 36823188, 2023). "For example, glutamine-dependent pancreatic ductal adenocarcinoma (PDAC) cells require MDH1 to maintain the cellular redox state by reprogramming the glutamine metabolism, and knocking down MDH1 compromises the survival of PDAC cells." (PMID 34829545, 2021). "In pancreatic ductal adenocarcinoma (PDAC), the knockdown of MDH1 or inhibition of its activity could repress mitochondria respiration and influence glutamine metabolism, which enhances tumor cells’ sensitivity to oxidative stress and suppresses proliferation." (PMID 32272554, 2020).
pancreatic cancer (11 papers, 2017 to 2025). "Recent studies have demonstrated that dysregulated MDH1 is associated with cancer progression, metabolic reprogramming, and therapy resistance in pancreatic cancer, breast cancer, and lung adenocarcinoma." (PMID 40626007, 2025). "The MAS is a key process in the cell to connect metabolic pathways in the mitochondria and the cytoplasm and has been linked to cancer metabolism, for example in pancreatic cancer or non-small lung cancer where amplification of Malate dehydrogenase 1 (MDH1) was detected." (PMID 37062524, 2023). "Carm1-mediated arginine methylation of MDH1 inhibits glutamine metabolism, thereby inhibiting the growth of pancreatic cancer." (PMID 36968582, 2023). "Wang showed that methylation of MDH1 by CARM1 inhibited glutamine metabolism in pancreatic cancer cells." (PMID 37649137, 2023). "Consistently, inhibition of MDH1 activity leads to suppression of glutamine metabolism and reduction of pancreatic cancer cell growth." (PMID 29295482, 2017). "At the same time, they also observed that the expression of CARM1 in pancreatic cancer is significantly lower than in normal tissue, accompanied by the activation of MDH1, revealing the important role of CARM1 in regulating pancreatic cancer metabolism through MDH1 methylation." (PMID 39964832, 2025). "A recent study suggests that methylation on arginine 248 inhibits MDH1 catalytic activity and dimerization by coactivator-associated arginine methyltransferase 1 (CARM1), and KRAS suppresses CARM1-mediated MDH1 methylation, contributing to glutamine metabolism in pancreatic cancer." (PMID 33117704, 2020). "However, the expression of PRMT4 protein is significantly suppressed in pancreatic cancer cells, resulting in reduced asymmetric arginine dimethylation of malate dehydrogenase 1 (MDH1) and enhanced non-canonical glutamine metabolism." (PMID 33344439, 2020). "Pancreatic cancer cells rely on a cytoplasmic glutaminolysis pathway producing pyruvate, which requires aspartate transaminase (GOT1, catalyzes aspartate to oxaloacetate), malate dehydrogenase (MDH1, catalyzes malate/oxaloacetate), and malate enzyme (ME1, catalyzes malate/pyruvate)." (PMID 29295482, 2017).
lung carcinoma (7 papers, 2018 to 2025). "In this study, a novel series of dual MDH1/2 inhibitors for lung cancer was rationally designed and synthesized, and their SAR was carefully investigated." (PMID 37242466, 2023). "In this study, to develop a potent dual inhibitor of MDH1/2 for lung cancer, LW1497 derivatives were synthesized based on their structure–activity relationships (SARs)." (PMID 37242466, 2023). "In this study, we synthesized compound 50, a potent MDH1/MDH2 dual inhibitor that suppressed MAS function in A549 lung cancer cells." (PMID 37242466, 2023). "The association of MDH1 and MDH2 have been reported in several cancers such as pancreatic and lung cancers." (PMID 37242466, 2023). "LW1497, a malate dehydrogenase 1/2 inhibitor, blocks the TGF-β1-induced EMT of A549 cells via Slug downregulation and thereby suppresses the progression of the lung cancer caused by transplanted A549 cells in mice." (PMID 34829545, 2021). "Collectively, these results indicate that compound 50 may pave the way for the development of next-generation dual MDH1/2 inhibitors to target lung cancer." (PMID 37242466, 2023). "To accelerate the clinical translation of MDH1 as a predictive biomarker, we next interrogated whether MDH1 expression levels modulate drug sensitivity by comparing the IC50 values of standard-of-care antineoplastic agents across lung-cancer cell lines stratified into MDH1-high and MDH1-low cohorts." (PMID 40948768, 2025). "Finally, we identified compound 50 as a dual inhibitor of MDH1/2 in lung cancer cells." (PMID 37242466, 2023). "Therefore, compound 50, now LW2393, may serve as a promising lead for the development of novel MDH1/2 inhibitors for the treatment of lung cancer." (PMID 37242466, 2023). "Investigators have successfully synthesized compound 50, which functions as a potent inhibitor of both MDH1 and MDH2, thereby inhibiting the activity of the MAS in A549 lung cancer cells, as documented in the literature." (PMID 40948768, 2025). "Our findings provide the first evidence that MDH1 may contribute to NSCLC progression through circRNA/miRNA-mediated regulation, highlighting a novel metabolic node in lung cancer biology." (PMID 40626007, 2025). "The expression levels of MDH1 and MDH2 are high in patients with lung cancer." (PMID 37242466, 2023). "MDH1 and MDH2 enzymes play an important role in the survival of lung cancer." (PMID 37242466, 2023). "Furthermore, our study concurs with the finding that MDH1, but not MDH2, is required for proliferation of lung cancer cell lines." (PMID 29452638, 2018).
glioblastoma (5 papers, 2011 to 2025). The most malignant astrocytic tumor (WHO grade IV). "We performed the dual reporter assay in HeLa cells and two glioblastoma cell lines, U118 and U373, and compared MDH1 and LDHB readthrough." (PMID 27881739, 2016). "MDH1 readthrough was present in all cell types analysed in our study, and was found to be highest in U118 glioblastoma cells." (PMID 27881739, 2016). "In the present study, we evidenced that MDH1 was nearly undetectable by Western blot in our glioblastoma lysates." (PMID 21655185, 2011). "Moreover, MDH1, the target of several deregulated microRNAs, is repressed in glioblastomas, making an intramitochondrial-NAD reduction mediated by the mitochondrial aspartate-malate shuttle unlikely." (PMID 21655185, 2011). "Furthermore, to test whether functional readthrough of the MDH1 stop codon is a general property, we stained endogenous MDH1 in two glioblastoma cell lines, U118 and U373, and in murine cardiomyocytes." (PMID 27881739, 2016). "MDH1 is also known to contain a functional hidden PTS1 in the extension and endogenous MDH1 is present in the peroxisomes of HeLa cells, HEK cells, glioblastoma cell lines and murine cardiomyocytes." (PMID 27881739, 2016). "The lack of MDH1 in primary glioblastoma cells can impair mitochondrial NAD reduction through the aspartate-malate shuttle." (PMID 38786726, 2024). "The absence of MDH1 in primary glioblastomas may dramatically impair the mitochondrial NAD reduction through the aspartate-malate shuttle." (PMID 21655185, 2011).
glioma (5 papers, 2011 to 2025). A benign or malignant brain and spinal cord tumor that arises from glial cells (astrocytes, oligodendrocytes, ependymal cells). "If this glutamate-dependent acetyl-CoA generation pathway functions in glial cells, in gliomas the mutations of IDH1 or the low amounts of MDH1 are expected to reduce the concomitant production of acetyl-CoA and oxaloacetate through this pathway." (PMID 21655185, 2011). "These GASCs, which are of prognostic value in glioma, may undergo metabolic reprogramming and induce the metabolic reprogramming of GB cells through MDH1." (PMID 38803161, 2024). "In conclusion, modified amounts of active SIRT1, IDH1 and MDH1 in gliomas may interfere with acetyl-CoA production." (PMID 21655185, 2011). "miR-15b, miR-16, miR-26b and miR-126, all four miRNAs that we found over-expressed in gliomas, putatively target MDH1 and may contribute to its down-regulation." (PMID 21655185, 2011). "Immune-related pathways such as TNF signalling (IDH3B/G, MDH1, ACO2, SDHA, OGDHL) and JAK/STAT3 (PIAS2/3, PTPN2, AKT1/2, MCL1, CISH, AOX1) signalling are enriched in gliomas and play a critical role in their progression." (PMID 41007296, 2025). "For example, lower amounts than expected regarding mRNA levels are noted for MDH1 in GBM and SIRT1 in gliomas; or the protein concentration was increased in glioma tissues, although the mRNA was only slightly modified (typically CCPG1, BCL2, MDM2 and PTBP1)." (PMID 21655185, 2011). "However, there is no direct experimental evidence showing that MDH1 works as a new RBP participating in glioma progression." (PMID 32272554, 2020).
schizophrenia (5 papers, 2008 to 2016). A major psychotic disorder characterized by abnormalities in the perception or expression of reality. "Dysregulation of the Krebs cycle has also been implicated in schizophrenia as a result of differential abundance of several involved enzymes: such as aconitase 2 (ACO2), malate dehydrogenase 1 (MDH1), and citrate synthase (CS)." (PMID 26909022, 2016). "For MDH1, the expression is significantly decreased in the schizophrenia group of both sexes suggesting that this gene might be down-regulated in schizophrenia regardless of sex." (PMID 26818902, 2016). "Previous research has implicated metabolic and mitochondrial genes, including ornithine aminotransferase (OAT) and metabolic enzyme cytosolic malate dehydrogenase (MDH1) in schizophrenia, which have not been shown to be influenced by cigarette smoking or antipsychotic treatment." (PMID 19772658, 2009).
acute liver failure (3 papers, 2024 to 2025). Rapid deterioration of liver function causing encephalopathy and coagulopathy. "IDH1-K93 and MDH1-K118 mutations reduce acetylation of IDH1 and MDH1, which promotes the formation of NETs and aggravates the progression of acute liver failure." (PMID 38172700, 2024). "In a mouse model of ALF, deacetylation of IDH1 and MDH1 resulted in NETosis and promoted the progression of acute liver failure." (PMID 38172700, 2024). "Therefore, we speculate that deacetylation of IDH1 and MDH1 may promote acute liver failure by regulating NETosis." (PMID 38172700, 2024). "Under deacetylation conditions, malate dehydrogenase 1 (MDH1) and isocitrate dehydrogenase 1 (IDH1) activate ER stress signaling, amplifying PANoptosis in acute liver failure." (PMID 40831559, 2025).
breast carcinoma (3 papers, 2021 to 2025). "Knocking down MDH1 also inhibits fatty-acid synthesis, reducing the survival rate of BT474 cells, which are Erb-B2 receptor tyrosine kinase 2 (ERBB2)-positive breast cancer cells." (PMID 34829545, 2021).
candidiasis (3 papers, 2021 to 2024). Infection with the organism Candida. "Mdh1 has been identified as a potential vaccine antigen for candidiasis due to its consistent presence throughout the investigated time points and lack of significant variation in relative abundance." (PMID 38404288, 2024). "C. albicans malate dehydrogenase (Mdh1) has been screened by few proteome studies as a candidate for a vaccine against candidiasis." (PMID 34696267, 2021). "Investigations into the use of recombinant Mdh1 as a candidate antigen for a candidiasis vaccine have demonstrated that subcutaneous and intradermal administration in mice elicits significantly elevated antibody responses and confers significant protection against candidiasis." (PMID 38404288, 2024).
lung adenocarcinoma (3 papers, 2023 to 2025). A carcinoma that arises from the lung and is characterized by the presence of malignant glandular epithelial cells. "Complementary in-vitro experiments have corroborated its pro-tumorigenic impact in lung adenocarcinoma, while high-throughput drug profiling has nominated small-molecule activators of MDH1 for potential therapeutic exploitation." (PMID 40948768, 2025). "Experiments have also been conducted to investigate the biological function of MDH1 in lung adenocarcinoma (LUAD) and to confirm the interaction between MDH1 and macrophages using immunofluorescence assays." (PMID 40948768, 2025). "Our observations indicate a positive correlation between elevated MDH1 levels and increased immune cell infiltration, activation of CD8+ T cells, and enhanced interferon-gamma (IFN-γ) response in lung adenocarcinoma (LUAD)." (PMID 40948768, 2025). "Both MDH1/2 and GOT1/2 are highly expressed in the malate-aspartic acid shuttle pathway of lung adenocarcinoma, and the high expression of GOT2 may promote the occurrence and malignant progression of lung adenocarcinoma." (PMID 37065159, 2023).
lung squamous cell carcinoma (3 papers, 2020 to 2025). "MDH1 is predicted to be a prognostic marker of lung squamous cell carcinoma (LUSC) based on multivariate Cox regression analysis." (PMID 37151882, 2023). "Strikingly, they found amplification of the MDH1 locus in 11% of the squamous cell lung cancer specimens, and they provide evidence that this is indeed due to selection for increased MDH1 activity." (PMID 32916028, 2020).